EZH2 (enhancer of zeste 2 polycomb repressive complex 2 subunit)
Diseases named in the same sentence as EZH2 in open-access papers (continued):
Sharing a sentence is not in itself a finding about the gene and the disease.
epithelioid sarcoma (continued). "Tazemetostat, initially FDA-approved for epithelioid sarcoma, is an epigenetic regulator and an EZH2 inhibitor that is expressed in various neoplasms." (PMID 38136345, 2023). "Tazemetostat is a small molecule EZH2 inhibitor that is clinically approved for the treatment of epithelioid sarcoma." (PMID 37572850, 2023). "Tazemetostat, a EZH2 inhibitor that has shown to be active in epithelioid sarcoma (EpS), has been also investigated in other solid tumors harboring alterations in EZH2 or the SWI/SNF complex." (PMID 36979853, 2023). "An innovative therapy for epithelioid sarcoma indicates that EZH2 inhibitors show very promising prospects for the treatment of solid tumors that have been difficult to achieve by previously developed epigenetics-based drugs." (PMID 37394582, 2023). "Inhibition of Enhancer of Zeste 2 (EZH2), a type of HMT, has been proven effective for metastatic or locally advanced epithelioid sarcoma and it is for this indication that the EZH2 inhibitor tazemetostat has been approved by the FDA." (PMID 36980741, 2023). "Agents that inhibit EZH2 are being clinically evaluated in a variety of tumor types, and one EZH2 inhibitor has been approved for the treatment of epithelioid sarcomas." (PMID 37104245, 2023). "Accordingly, the EZH2-specific inhibitor EPZ6438 was already approved for the treatment of epithelioid sarcoma by FDA." (PMID 37297005, 2023). "Currently, there is only one EZH2 inhibitor tazemetostat approved by FDA for advanced epithelioid sarcoma and follicular lymphoma while other EZH2 inhibitors are still being tested in phase I/II clinical trials." (PMID 36198685, 2022). "Perhaps the best known is that of tazemetostat, an EZH2 inhibitor approved in unresectable epithelioid sarcoma, the first FDA-approved epigenetic therapy in a solid tumor." (PMID 35582536, 2022). "EZH2 is expressed in approximately one-third of epithelioid sarcomas, making EZH2 a promising target." (PMID 36209184, 2022). "We used tazemetostat, a potent and selective competitive inhibitor of EZH2 approved for treatment of epithelioid sarcoma, to explore the antiviral potential of stand‐alone EZH2 inhibition against SARS‐CoV‐2." (PMID 35833542, 2022). "The indications are mainly for patients with advanced or extensive metastatic epithelioid sarcoma who are unable to undergo radical surgery, which is a landmark in EZH2 inhibitor development." (PMID 35257481, 2022). "In 2020, the Food and Drug Administration (FDA) approved the first EZH2 inhibitor tazemetostat (EPZ-6438) for the treatment of metastatic or locally advanced epithelioid sarcoma." (PMID 36077742, 2022). "In fact, the EZH2 inhibitor tazemetostat was approved by the FDA in 2020 for the treatment of advanced epithelioid sarcoma." (PMID 35852858, 2022). "Most new drugs targeting EZH2 are still in the preclinical phase or phase 1/2 of clinical trials, but tazemetostat was approved for the treatment of epithelioid sarcoma (ES) and preliminarily showed promising effects on follicular lymphoma (FL)." (PMID 36313363, 2022). "Till now, tazemetostat stands as the only approved EZH2 inhibitor for advanced epithelioid sarcoma, however, various EZH2 inhibitors are being evaluated at preclinical and clinical stages." (PMID 33840388, 2021). "Sitaxentan, an EZH2 inhibitor, has been approved for treating epithelioid sarcoma as the first FDA-approved EZH2 inhibitor." (PMID 34288823, 2021). "In 2020, the FDA approved the use of tazemetostat (TazverikTM), a small molecule inhibiting EZH2, for the treatment of epithelioid sarcoma." (PMID 34577136, 2021). "Recently, EPZ‐6438 has been approved by FDA as the first EZH2 inhibitor for the treatment of epithelioid sarcoma, and EPZ‐6438 treatment inhibited the progression of several cancers." (PMID 34031939, 2021). "Tazemetostat is the first approved EZH2 inhibitor and also the first therapy specifically for the treatment of epithelioid sarcoma." (PMID 34054126, 2021).
epithelioid sarcoma (continued). "The approval of an epigenetic agent (EZH2 inhibitor, tazemetostat) in treatment of a rare soft tissue malignancy, epithelioid sarcoma, is a solid step towards the future breakthrough in the mechanism based solid tumor epigenetic treatment." (PMID 33879235, 2021). "Tazemetostat is the first-in-class, small molecule enhancer of zeste homolog 2 (EZH2) inhibitor approved in the United States in January 2020 to treat locally advanced or metastatic epithelioid sarcoma." (PMID 33072594, 2020). "More importantly, the loss of SMARCB1/INI1 leads to the deregulation of EZH2, and drugs targeting EZH2 have been proven successful in controlling tumor growth and are currently approved to be used in treating epithelioid sarcoma." (PMID 33072594, 2020). "Tazemetostat, a specific EZH2 inhibitor, has just been approved for patients with advanced epithelioid sarcoma and represents a new therapeutic option in this devastating disease." (PMID 32264965, 2020). "Tazemetostat, an EZH2 inhibitor, has been approved for treating epithelioid sarcoma, and it is the first EZH2 inhibitor approved by FDA." (PMID 32206036, 2020). "On the therapeutic front, there has been important progress: in a pivotal phase II trial, the EZH2 inhibitor tazemetostat demonstrated clinical activity in patients with advanced or metastatic epithelioid sarcoma, showing an objective response rate of around 15% and a manageable safety profile." (PMID 41008921, 2025). "Consequently, inhibitors of EZH2 such as tazemetostat, which has recently entered into clinical use for epithelioid sarcoma, has attracted a lot of interest and has recently demonstrated some promising results of efficacy in preliminary clinical trials." (PMID 36900330, 2023). "Over 90% of epithelioid sarcoma cases are characterized by loss of INI1 (also known as SMARCB1), conferring an oncogenic dependency on the enhancer of zeste homolog 2 (EZH2), the catalytic subunit of the chromatin remodeling polycomb repressive complex 2 (PRC2)." (PMID 37998367, 2023). "Agents targeting EZH2 have shown to induce tumor regression and promote radiation sensitivity in models of SMARCB1/INI1-deficient tumors, including poorly differentiated chordomas, malignant rhabdoid tumors and epithelioid sarcomas." (PMID 37456229, 2023). "However, treatment with tazemetostat, an EZH2 inhibitor that has recently been entered into the clinical treatment for epithelioid sarcoma, showed only a modest response rate in patients with relapsed or refractory BAP1-inactivated mutations." (PMID 36900330, 2023). "In addition, the efficacy of EZH2 inhibitors in patients with advanced SMARCB1-negative epithelioid sarcoma has been reported." (PMID 36732357, 2023). "In epithelioid sarcoma, we observed success using EZH2 inhibitor tazemetostat." (PMID 34638300, 2021). "Interestingly, we found only limited sensitivity to EZH2 inhibition in A204 rhabdoid tumor, and resistance in epithelioid sarcoma cells." (PMID 34281526, 2021). "Tazemetostat competitively inhibits EZH2, stopping epithelioid sarcoma growth." (PMID 32722580, 2020). "As EZH2 enzymatic gain-of-function is associated with various cancer types, several selective EZH2 inhibitors have been developed and investigated, with Tazemetostat as the first inhibitor approved in early 2020 by the FDA to target epithelioid sarcoma." (PMID 32650416, 2020). "Here, we examined the mechanistic effects of Tazemetostat (EPZ6438), an Food and Drug Administration approved Ezh2 inhibitor for epithelioid sarcoma treatment, because this drug could potentially be repurposed to stimulate osteogenesis for clinical indications." (PMID 37572850, 2023). "EZH2 encodes a core component of PRC2, but might exert PRC2-independent oncogenic activity, and the EZH2 inhibitor tazemetostat has been approved by the US Food and Drug Administration for treatment of advanced epithelioid sarcomas with EZH2 mutation." (PMID 37837931, 2023).
epithelioid sarcoma (continued). "Tazemetostat, which was recently approved as an inhibitor of EZH2, a histone H3K27 selective methyltransferase, has shown positive effects not only in epithelioid sarcoma but also in a variety of drug-resistant cancers." (PMID 37394580, 2023). "In January 2020, a significant milestone was achieved with the approval of tazemetostat, an inhibitor targeting KMT6A (EZH2), for the treatment of epithelioid sarcoma." (PMID 38077327, 2023). "Metastatic epithelioid sarcoma (EPS) remains a largely unmet clinical need in children, adolescents and young adults despite the advent of EZH2 inhibitor tazemetostat." (PMID 35839307, 2022). "In 2020, a first-in-class, orally bioavailable EZH2 inhibitor, tazemetostat, received accelerated approval by FDA, for treatment of epithelioid sarcoma." (PMID 35137163, 2022). "Furthermore, given the outstanding inhibition of tumor growth demonstrated by EZH2 inhibitors in combination with anti-PD-1 therapy, Tazemetostat has been approved as the most widely studied EZH2 inhibitor as a first-line treatment option for epithelioid sarcoma." (PMID 36685594, 2022). "EZH2 activation is involved in DFSP, MPNST, angiosarcoma, Kaposi’s sarcoma, leiomyosarcoma, epithelioid sarcoma, and synovial sarcoma." (PMID 35008848, 2021). "Recently, the FDA has approved tazemetostat, the first inhibitor of EZH2 (a top core regulator in GII), for treating epithelioid sarcoma, indicating EZH2 as a potential target in LUAD." (PMID 34001209, 2021). "A clear example is an inhibitor of enhancer of zeste homolog 2 (EZH2) histone methyltransferase, tazemetostat, registered in the USA for metastatic or locally advanced unresectable epithelioid sarcoma." (PMID 32722580, 2020). "In this context, EZH2 has emerged as an important target for the development of various inhibitors, including Tazemetostat (TAZ; Tazveric, EPZ-6438), a first-in-class potent and selective EZH2 inhibitor used in the treatment of advanced epithelioid sarcoma." (PMID 38473991, 2024). "Recent clinical trials have identified tazemetostat, an EZH2 inhibitor, as promising monotherapy treatment for proximal and distal EPS, with 9 of 62 epithelioid sarcoma patients (∼15%) demonstrating objective response to tazemetostat, although all responders were classified as partial responders." (PMID 35839307, 2022). "Recently, the FDA has approved tazemetostat, an EZH2 methyltransferase, for the treatment of adults and pediatric patients aged 16 years and older with metastatic or locally advanced epithelioid sarcoma not eligible for radical resection." (PMID 32751241, 2020). "Tazemetostat (Tazverik), is an oral EZH2 inhibitor approved by the U.S. Food and Drug Administration (FDA), for the treatment of follicular lymphoma (FL) and epithelioid sarcoma (ES)." (PMID 40959108, 2025). "EZH2 inhibitors (EZH2i), a class of small-molecule inhibitors that target EZH2 to exert anti-tumor functions, have just been approved by the US Food and Drug Administration (FDA) in treatment of adults and adolescents with locally advanced or metastatic epithelioid sarcoma." (PMID 35432300, 2022). "The anti-proliferative effect of EZH2 inhibitor EPZ011989–8 and pan-HDAC inhibitors vorinostat, panobinostat (hydroxamates), and mocetinostat (benzamide) were screened using live cell imaging (IncuCyte ZOOM®) and/or MTS in VAESBJ and GRU1 epithelioid sarcoma and A204 rhabdoid tumor cell lines." (PMID 34281526, 2021). "Recently, the Food and Drug Administration (FDA) has approved tazemetostat, an EZH2 inhibitor, for the treatment of adults and pediatric patients aged 16 years and older with metastatic or locally advanced epithelioid sarcoma not eligible for radical resection." (PMID 32751241, 2020). "EPZ6438 (Tazemetostat) is a potent and selective SAM-competitive EZH2 inhibitor (EZH2i), approved by the FDA to treat patients with metastatic or locally advanced epithelioid sarcoma not eligible for complete resection." (PMID 41318657, 2025).
epithelioid sarcoma (continued). "In 2020, tazemetostat (Tazverik), a first-in-class small molecule EZH2 inhibitor, was granted accelerated approval by the FDA for patients with advanced or metastatic epithelioid sarcoma who are not eligible for curative surgery." (PMID 38268926, 2023).
liver cancer (91 papers, 2005 to 2026). An epithelial or non-epithelial malignant neoplasm that arises from the liver. "To assess potential cancer risk, we compared the liver transcriptome of aged mice with EZH2 overexpression with that from mouse liver cancer models." (PMID 41512022, 2026). "Our results demonstrated that histopathological imaging features were associated with differences in EZH2 expression levels and OS in liver cancer." (PMID 39640777, 2024). "The second pathway is targeting the enhancer of Zeste homologue-2 (EZH2) that can cause downregulation of multiple tumour suppressors, thus promoting liver cancer metastasis." (PMID 39320855, 2024). "lncRNA for β-catenin methylation (lnc-β-Catm) was upregulated in liver cancer stem cells (CSCs) and induced the methylation of β-catenin by associating with β-catenin and methyltransferase EZH2." (PMID 38203767, 2024). "Although EZH2 is overexpressed in many solid cancers, including breast, lung, and liver cancer, loss-of-function mutations of EZH2, inactivating mutations, or deletion of this epigenetic modifier is commonly present in human T-ALL cells." (PMID 36060800, 2022). "Our group has previously studied the functions of EZH2 in cancer, demonstrating that aberrant upregulation of EZH2 was associated with vascular invasion and multidrug-resistance of liver cancer." (PMID 26452129, 2015). "In the present study, to investigate the molecular mechanisms underlying the anticancer effects of EZH2 inhibitors, miRNA expression profiles in gastric and liver cancer cells were analyzed after treatment with SAHA and DZNep." (PMID 24861464, 2014). "As early as 2005, EZH2 was found to be associated with liver cancer." (PMID 37268997, 2023). "Finally, survival analysis, based on clinical information from the TCGA-liver cancer datasets, revealed that the high expression of EZH2, GINS1, and TPX2 correlated positively with higher risk, CENPF and BUB1B were quite the contrary." (PMID 30100882, 2018). "This suggests that EZH2 may be a risk factor associated with the prognosis of liver cancer." (PMID 39640777, 2024). "Moreover, further study revealed that CDK20 results in EZH2 (zeste homolog 2) upregulation and may be associated with poor survival in liver cancer." (PMID 33868579, 2021). "Further, Ezh1/Ezh2 deficiency in male liver, and to a lesser extent in female liver, led to up regulation of many genes linked to liver fibrosis and liver cancer, which may contribute to the observed liver pathologies and the increased sensitivity of these mice to hepatotoxin exposure." (PMID 32428001, 2020). "Specifically, ANXA2 and EZH2 have been identified as key regulators in the proliferation and metastasis of liver cancer." (PMID 40018411, 2025). "Recent studies have further highlighted the potential of targeting EZH2 to refine therapeutic strategies for liver cancer." (PMID 39516467, 2024). "Targeted drugs have been developed for EZH2 in liver cancer therapy, such as DZnep and GSK126, which have been validated HCC cell lines and xenograft models." (PMID 39640777, 2024). "This review summarizes the function of EZH2, the mechanism of EZH2 in liver cancer, and the current possibility of using EZH2 as a potential therapeutic target for liver cancer." (PMID 37268997, 2023). "We inoculated HLF liver cancer cells transduced with a virus expressing inducible scramble-sgRNA or EZH2-sgRNA." (PMID 36185457, 2022). "EZH2 overexpression is a poor prognostic marker in various cancers, including liver cancer, and targeting EZH2 is an anticancer strategy." (PMID 35253323, 2022). "In view of the expression levels of EZH2 and miR-138-5p in liver cancer patients, we verified the changes in the radiosensitivity of HCC cells after changing the expression levels." (PMID 36071871, 2022). "Epigenetic silencing of Wnt antagonists by EZH2 contributes to Wnt/β‐catenin signaling activation and results in liver cancer cell proliferation." (PMID 35253323, 2022).